TNF (tumor necrosis factor)
Diseases named in the same sentence as TNF in open-access papers (continued):
Sharing a sentence is not in itself a finding about the gene and the disease.
Crohn disease (continued). "Thus, the effect of pentoxifylline was investigated on intestinal inflammation in IBD, showing that pentoxifylline downregulates in vitro TNF-α and IL-1β production by PBMCs and by intestinal organ cultures from patients with Crohn’s disease and ulcerative colitis." (PMID 36142518, 2022). "In a comparative effectiveness study of 754 older patients, vedolizumab use was associated with a higher risk of treatment failure compared with TNF antagonists, without any difference in risk of serious infections, particularly for patients with Crohn disease." (PMID 36178685, 2022). "Another report in an eight-year-old male with Crohn’s disease on Infliximab who presented with histoplasmosis and concurrent Pneumocystis pneumonia further raised the issue of pre-commencement screening for opportunistic infections in children receiving TNF-alpha inhibitors." (PMID 34209280, 2021). "Therefore the TNF-α blockade may directly reduce T cell capacity of CD154 expression in patients with Crohn disease." (PMID 28837666, 2017). "It is also difficult in clinical settings to differentiate whether the appearance of sarcoid-like granulomas during anti-TNF-α therapy be true paradoxical inflammations or intrathoracic manifestation of Crohn’s disease or co-existence of Crohn’s disease and sarcoidosis." (PMID 26864464, 2016). "Histomorphometric analysis of bone samples in patients with different diseases affecting bone such as RA, Crohn’s disease, and bronchial asthma showed that eroded surface over bone surface (ES/BS), a parameter of bone resorption, was significantly increased in the context of high TNF-α levels." (PMID 24592264, 2014). "However, the absolute risk is small and does not negate the benefits of TNF-α inhibitors in severe Crohn’s disease." (PMID 24188588, 2013). "However, whether systemic or only local TNFα overproduction is required for the development of chronic intestinal inflammation and Crohn’s disease remains unclear." (PMID 23977323, 2013). "Interestingly we found that, while creeping fat releases higher levels of leptin, IL-6 and TNFα compared to the MAT explants obtained from Crohn's disease patients, incubation with VSL#3-CM conter-regulates the production of these inflammatory mediators and abrogates the generation of leptin." (PMID 21829567, 2011). "In Crohn's disease patients creeping fat is infiltrated by activated macrophages and releases high amount of TNF-α and leptin, a proinflammatory adipokine, indicating that this tissue could play a mechanistic role in maintaining local and systemic inflammation." (PMID 21829567, 2011). "In autoimmunity, anti-tumor necrosis factor (TNF) antibody adalimumab used in the treatment of ulcerative colitis and Crohn’s disease remains the top-selling monoclonal." (PMID 39563034, 2025). "Pro-inflammatory cytokines such as TNF-α and IFN-α upregulate PML expression in intestinal tissues of IBD patients, especially in Crohn’s disease." (PMID 41312366, 2025). "In 2008, certolizumab pegol (another anti‐TNF alpha inhibitor) was approved by the US Food and Drug Administration (FDA) for treating patients with Crohn's disease." (PMID 40772520, 2025). "Tumor necrosis factor-alpha (TNF-α) inhibitors, such as infliximab (IFX) and adalimumab, are proinflammatory cytokines that are effective against moderate and severe Crohn’s disease and ulcerative colitis." (PMID 39487903, 2025). "Differences in the molecular mechanisms by which TNF and IFN-γ mediate cell killing have been identified between pancreatic β cells in Type 1 diabetes and intestinal epithelial cells in Crohn’s disease." (PMID 40148285, 2025). "Converse to its protective effects, IL-22 also promotes the expression of proinflammatory cytokines tumor necrosis factor (TNF)-α and IL-8 in IECs and these cytokines in turn increase IL-22R1 expression, which may further strengthen the proinflammatory effect of IL-22 in inducing Crohn's disease." (PMID 41467015, 2025).
Crohn disease (continued). "The expression of mRNA encoding inflammatory cytokines (IL2, IL17A, IL17F, IL22, IFNG, TNF, CSF2 and LTA) in CD4+ TRM cells was comparable between healthy controls and patients with Crohn’s disease." (PMID 40050432, 2025). "For example, there is a positive correlation between RhoA and TNF-α in the intestinal inflammatory tissues of Crohn’s disease patients, and RhoA/ROCK pathway activation stimulates the production of TNF-α and IL-1β." (PMID 38355537, 2024). "STAT3 expression is induced by TNF-α, and STAT3 levels are increased in the tissues of ulcerative colitis and Crohn’s disease patients." (PMID 38091316, 2023). "Two TNFα inhibitors, infliximab and adalimumab, have been approved by the FDA for the treatment of moderate-to-severe Crohn’s disease and ulcerative colitis." (PMID 37764213, 2023). "Aims and Methods: In this retrospective multicenter cohort study, We aim to investigate the effectiveness of anti-TNF and UST as second-line therapy in patients with Crohn’s disease (CD) who failed VDZ as a first-line treatment." (PMID 37048587, 2023). "Immunosuppressive agents (such as anti-tumor necrosis factor-α, anti-TNF-α) can suppress the proliferation of inflammatory cells, and they are generally used in the treatment of patients with Crohn’s disease (CD)." (PMID 37238746, 2023). "This consideration arose from the discovery that in DD, as well as IBD, there is overexpression of the tumor necrosis factor (TNF)-α and a pro-fibrotic pattern that resembles that found in Crohn’s disease (CD)." (PMID 36499127, 2022). "ELISA was carried out to examine the expression of TNF-α, IL-1β, IL-6, CRP, SSA, AAT, AAG and HPT in the peripheral blood of patients with Crohn’s disease." (PMID 35422450, 2022). "Our results provide new treatment targets, for example, the MAPK pathway in all types of IBD, in ileal Crohn’s disease the JAK-STAT1/2 pathway, and in patients refractory to anti-TNFα treatment the NFκB, TGFβ, and JAK-STAT3 pathways." (PMID 37090899, 2022). "With tumor necrosis factor alpha (TNF-α) being a key cytokine of inflammation, anti-TNF therapies such as infliximab and adalimumab have started to dominate the treatment of Crohn’s disease." (PMID 36145641, 2022). "The effectiveness of ustekinumab (UST) in the treatment of Crohn’s disease (CD) has been demonstrated in the pivotal Phase 3 UNITI 1 and 2 and IM-UNITI studies in both anti-TNF-naïve and anti-TNF-exposed patients." (PMID 35448949, 2022). "The most commonly used dual biological therapy consisted of an anti-TNF agent and a newer biologic but very limited primary evidence, such as case series, suggested that the use of ustekinumab and vedolizumab may be effective for refractory Crohn’s disease with fistula." (PMID 35407612, 2022). "Ultimately, the increase in TNFα aggravated the Crohn’s disease in the AGLCD patient, however this was attenuated with anti-TNFα based therapeutics." (PMID 36479348, 2022). "In Crohn’s disease (CD), TACE activity is upregulated, resulting in a marked increase of TNFα secretion and inflammation." (PMID 35585977, 2022). "To analyze the possible usefulness of AIF-1 as a biomarker in Crohn’s disease, we studied the levels of AIF-1 in a cohort of naïve patients treated with anti-TNF (infliximab or adalimumab)." (PMID 35327530, 2022). "We previously found elevated BAFF in serum, stool and colon tissue of adults with ulcerative colitis and Crohn’s disease, and serum BAFF levels correlated with disease activity, ESR, TNF-α, and IL-1β in ulcerative colitis patients." (PMID 35320937, 2022). "Background and Aims: Anti-tumor necrosis factor mAb (i.e., adalimumab, ADA) is currently used in the treatment of patients with Crohn’s disease (CD)." (PMID 36034848, 2022). "The proinflammatory cytokine tumor necrosis factor α (TNFα) plays a key role in the pathogenesis of IBD, and thus has been shown to be increased in patients with Crohn’s disease (CD) or ulcerative colitis (UC)." (PMID 34445450, 2021).
Crohn disease (continued). "A previous study reported that TNF-α induction increased intestinal epithelial tight junction permeability and could be considered an important proinflammatory mechanism contributing to intestinal inflammation in Crohn’s disease and other inflammatory conditions." (PMID 34162433, 2021). "Antibodies targeting tumor necrosis factor-alpha (anti-TNF) have become essential in the armamentarium for the treatment of both ulcerative colitis (UC) and Crohn’s disease (CD)." (PMID 34069295, 2021). "We report the case of a patient with Crohn's disease who developed SJS during an HSV1 infection and a contemporaneous anti-TNFα therapy with adalimumab." (PMID 32351742, 2020). "Treatment responses were followed by physical examination and Crohn's disease activity index (CDAI) scoring before and 2 weeks after the initial administration of anti‐TNF‐α antibodies." (PMID 32514440, 2020). "Anti‐tumor necrosis factor alpha (TNF‐α) therapy has been reported to be effective for induction and maintenance therapy for Crohn's disease (CD)." (PMID 32514440, 2020). "The details of the role of STAT1 in intestinal epithelium in the TNF model, but also in IBD and Crohn's disease, are being revealed, but await further detailed studies." (PMID 32914580, 2020). "Anti-TNFα therapy up-regulated IL6 and IL23p19, in patients with Crohn’s disease; IL-1B and IL17A remained up-regulated in patients refractory to anti-TNF α." (PMID 33193322, 2020). "Anti-tumor necrosis factor (TNF) therapy is used for the induction and maintenance of remission in Crohn’s disease (CD) patients." (PMID 32922288, 2020). "TNF plays a central role in IBD pathogenesis, which is evident by the current use of TNF inhibition for as a standard therapy for both Crohn’s disease and ulcerative colitis." (PMID 30498997, 2019). "A theoretical pharmacokinetic/pharmacodynamic model in which the degree of inflammation (reflected by the poor surrogate marker Crohn’s Disease Activity Index), changed by the binding of IFX to TNF in patients with CD was previously proposed." (PMID 31489538, 2019). "The role of TNF-α is established in the pathophysiology of IBD, and has been exploited by the use of anti-TNF therapy as a beneficial treatment for Crohn’s disease and UC." (PMID 31008013, 2019). "In 2016, the National Institute for Health and Care Excellence (NICE) published diagnostics guidance on TDM of TNF alpha inhibitors (IFX and ADAL) in Crohn disease (referred to as DG22)." (PMID 30341052, 2018). "Pediatric guidelines for Crohn's disease from ECCO and ESPGHAN are clear that testing for tuberculosis prior to starting an anti-TNF agent should by mandatory." (PMID 30009157, 2018). "In a Crohn’s disease model, CXCL10 blockade reduces serum IL-12p40, IL-2, IFN-γ, IL-1α, IL-1β, and TNF-α." (PMID 29910805, 2018). "Aims: determine if I-FABP is elevated in active Crohn's disease (CD) and if I-FABP parallels anti-TNFα antibody (infliximab) induced lowering of TNFα and Harvey-Bradshaw Index (HBI) as potential indicator of mucosal healing." (PMID 29201046, 2017). "Anti-tumour necrosis factor alpha (anti-TNF-α) inhibitors, such as infliximab and adalimumab, are commonly used to treat moderate to severe refractory IBD and fistulizing Crohn's disease." (PMID 27725926, 2016). "Anti-TNFα therapy induces sustained remission and short-term improvements in height velocity and/or height standard deviation score (H-SDS) patients with Crohn’s disease." (PMID 27636201, 2016). "In 1998, Infliximab, a chimeric monoclonal antibody against tumor necrosis factor alpha (TNF-α), was invented and approved for treatment of Crohn’s disease." (PMID 26450611, 2015). "These monoclonal antibodies, which target tumor necrosis factor (TNF), integrins or IL12/23, have been approved—or are in development for—both Crohn’s disease (CD) and ulcerative colitis (UC)." (PMID 25567472, 2015).
Crohn disease (continued). "This is in accordance with previous reports that have demonstrated that TNF α gene expression in colorectal mucosa and high serum TNF levels can be used as a predictor for IFX therapy in ulcerative colitis and Crohn’s disease, respectively." (PMID 25015298, 2014). "Patients with Crohn's disease have increased intestinal expression and activity of MLCK, implicating this TNF-mediated pathway in the reduced barrier function that is a feature of IBD." (PMID 22031828, 2011). "In 1998, the drug infliximab, developed from a murine-human chimeric anti-tumor necrosis factor (TNF) monoclonal antibody that binds diverse TNF moieties, was approved by the US Food and Drug Administration for the treatment of Crohn's disease." (PMID 19830122, 2009). "TNF-α involvement in the pathogenesis of IBD is reflected in local cytokine expression in the gut tissue, as well as the therapeutic efficacy of anti-TNF agents for both Crohn's disease (CD) and ulcerative colitis (UC)." (PMID 39807347, 2025). "Among the TNF-α inhibitors analyzed, adalimumab, certolizumab, and etanercept are approved by the FDA for polyarticular JIA in patients aged ≥2 years, while infliximab is approved for pediatric Crohn’s disease in children ≥6 years." (PMID 41329755, 2025). "Serum INF-γ levels were decreased after anti-TNF treatment in children with Crohn’s disease (CD), but not in those with ulcerative colitis (UC)." (PMID 40244207, 2025). "There is a unique population of TNFα + IL-17A + CD4 + T_RM cells in Crohn’s disease which are largely absent in controls." (PMID 38420127, 2024). "Overall, there were no significant DMPs at baseline between anti-TNF–naïve Crohn’s disease patients who were subsequently treated with infliximab or adalimumab." (PMID 37551994, 2024). "The levels of the analyzed biomarkers were measured before and after a year of anti-inflammatory treatment, which was a tumor necrosis factor α (TNF-α) inhibitor (adalimumab) in patients with ulcerative colitis (UC) and conventional therapy in patients with Crohn’s disease (CD)." (PMID 39407507, 2024). "Thus, anti-TNFα therapies, such as infliximab (IFX) and adalimumab (ADA), started to emerge and dominate the treatment of Crohn’s disease." (PMID 38931955, 2024). "Approximately 30–50% of patients with ulcerative colitis and around 15% of those with Crohn’s disease are treated with 5-aminosalicylate (5-ASA), while anti-Tumor Necrosis Factor α (TNF-α) is prescribed to roughly 20–40% of IBD patients, especially those with moderate to severe disease." (PMID 39768250, 2024). "The anti-TNF-alpha effect of the CAP could be used also in the treatment of chronic inflammatory bowel diseases, such as Crohn’s disease and ulcerative colitis, in which TNF-α plays a key role." (PMID 37821752, 2024). "Infliximab, a chimeric anti-tumor necrosis factor (TNF) antibody, was shown to induce monocyte apoptosis, which could explain its powerful properties in patients with chronically active Crohn’s disease." (PMID 38786041, 2024). "In Crohn’s disease, an IBD, TNFα disrupts the intestinal epithelial barrier function." (PMID 38150443, 2023). "At 5 years follow-up of patients who went straight to surgery, 26% required subsequent anti-TNF therapy; however, 29 (42%) required no further Crohn’s disease related medication." (PMID 37685662, 2023). "During the last two decades, monoclonal antibodies have played an increasing role in the treatment of Crohn’s disease; however, therapy with tumor necrosis factor (TNF)-inhibitors is challenging due to high rates of nonresponse and secondary loss of response." (PMID 37685662, 2023). "Real-world clinical studies have demonstrated ustekinumab’s superiority over anti-TNF drugs for anti-TNF experienced (non-biologic naïve) Crohn’s disease patients." (PMID 37941597, 2023).
Crohn disease (continued). "Furthermore, laminins are known to play a role in shaping the architecture of intestinal mucosa, and an altered expression has been observed in Crohn’s disease, a type of IBD, driven by pro-inflammatory cytokines TNF-α and IFN-γ53–55." (PMID 35501398, 2022). "They found that GPR183 mRNA as well as CH25H and CYP7B1 were increased in colon biopsy samples of UC patients vs. healthy controls, although Crohn’s disease patients and responsiveness to TNF blockade were not included in that analysis." (PMID 36389671, 2022). "In conclusion, our study demonstrated that the two SNPs, rs322931 (C>T) in miR-181b and rs7158663 (G>A) in MEG3, could aggravate the inflammatory response of anal abscess in patients with Crohn’s disease, via modulating the MEG3/miR-181b/TNF signaling pathway." (PMID 35422450, 2022). "Generally, Crohn’s disease has a T helper 1 (Th1) cytokine profile where the Th1 cells produce pro-inflammatory cytokines such as interferon-γ (IFN-γ), interleukin 2 (IL-2) and tumor necrosis factor α (TNF-α)." (PMID 35766160, 2022). "In this case-based review of the literature, we present a 36-year-old female patient diagnosed with Crohn’s disease (CD) and Coombs positive AIHA, complicated by pulmonary thromboembolism and successfully treated with anti-tumor necrosis factor (anti-TNF) therapy." (PMID 36362944, 2022). "Patients with ulcerative colitis (UC) (n = 21) and Crohn’s disease (CD) (n = 12) with non-response to biological therapy (anti-tumor necrosis factor (TNF) or vedolizumab) were included." (PMID 36384462, 2022). "We present a non-anti-TNF naïve patient suffering from severe Crohn's disease who developed DILI with a hepatocellular pattern, without jaundice, after two infusions of an IFX biosimilar." (PMID 36654618, 2022). "Ustekinumab, is a new therapy for patients with IBD, especially for patients suffering from Crohn’s disease (CD) who did not respond to anti-TNF treatment." (PMID 36584073, 2022). "In another study in a murine model of Crohn's disease, UCN could control inflammatory diseases by inhibiting a wide range of inflammatory cytokines such as TNF-α, IFN‐γ, IL-6, IL-1α, IL-1β, IL-12, IL-18, IL-17, and IL-15." (PMID 35419072, 2022). "The concentration of iFABP in patients with Crohn’s disease has also been shown to correlate with the pro-inflammatory cytokine tumour necrosis factor (TNF)-α and significantly decrease during treatment with anti-TNF-α therapy." (PMID 35606704, 2022). "Despite the strong available evidence that anti-tumor necrosis factor (anti-TNF) agents are useful in the treatment of perianal fistulizing Crohn’s disease (PFCD), a significant number of these patients do not respond to therapy." (PMID 35407421, 2022). "In the TNBS model of male Wistar rats’ model of Crohn’s disease, oral administration of nicotine (5 μg/ml, 10-day pretreatment or 3 days after induction, in drinking water) reduced macroscopic damage with a reduction in MPO, iNOS, TNFα, and LTB4." (PMID 35251010, 2022). "Treatment with an anti-TNF agent or an immunomodulator for 1–6 months can improve the depressive state of patients with Crohn’s disease regardless of the disease activity." (PMID 33498197, 2021). "In humans, IL11 is highly upregulated in the colonic mucosa of patients with either ulcerative colitis or Crohn’s disease who do not respond to anti-TNF therapy, with recent single cell RNA-seq studies localizing IL11 to inflammatory mucosal stromal cells." (PMID 31917819, 2020). "Notably, A. absinthium extracts was reported to reduce tumor necrosis factor-alpha (TNF-α) and provide synergistic action on healing in patients with Crohn’s disease." (PMID 32585887, 2020). "TNF-α antagonists, including anti-TNF receptor antibodies and anti-IL-6 receptor antibodies, are currently used to inhibit the action of each proinflammatory cytokine for the treatment of RA and Crohn’s disease." (PMID 32183436, 2020).